GSK3B (glycogen synthase kinase 3 beta)
Diseases named in the same sentence as GSK3B in open-access papers (continued):
Sharing a sentence is not in itself a finding about the gene and the disease.
Alzheimer disease (continued). "In particular, it was reported that the serine/threonine kinases GSK-3β and Akt are involved in the molecular pathophysiology of many mitochondria-related diseases and pathological conditions, such as Alzheimer’s disease and Parkinson’s disease, and also numerous pathologies of the heart." (PMID 32722345, 2020). "Finally, in Alzheimer's disease, Sch B was reported to reduce GSK-3β, a key enzyme necessary for the hyperphosphorylation of tan protein, therefore contributing to the protection of neurons from Alzheimer's diseases." (PMID 32256947, 2020). "Recently, increasing evidence has shown that GSK-3β may be a key link between diabetes mellitus (DM) and Alzheimer’s disease (AD), where GSK-3β controls glycogen synthesis, thereby regulating blood glucose." (PMID 33126517, 2020). "Interestingly, the authors found that anthocyanin-loaded PEG-AuNPs (PEG-AuNPs) were more effective than native anthocyanins in reducing the neuropathological disorder of Alzheimer’s disease via the PI3K/p-Akt/p-GSK3β pathway." (PMID 31141884, 2019). "In addition, GSK3β, a key node of the networks, was significantly regulated, which has been showed to play a critical role in the pathogenesis of Alzheimer’s disease by promoting Aβ generation and Tau hyperphosphorylation." (PMID 31036051, 2019). "GSK3B is a known drug target for Alzheimer's disease andbreastcancer." (PMID 31354196, 2019). "PI3K/Akt-GSK3β signaling contributes to neuronal growth, proliferation, and differentiation of NSCs; promotes hippocampal neurogenesis in a mouse model of Alzheimer’s disease; and ameliorates the apoptosis of neuronal cells in a rat model of Parkinson’s disease." (PMID 31779687, 2019). "In addition, the altered Akt/GSK3β signaling in Ngl3−/− mice, known to affect numerous synaptic and non-synaptic target proteins and be associated with various brain disorders, including schizophrenia, Alzheimer disease, and bipolar disorder, may alter the synaptic, neuronal, and circuit functions." (PMID 31166939, 2019). "Progressively decreasing LMTK2 levels seen in an Alzheimer’s disease mouse model could potentially lead to aberrant overactivation of GSK3β in aged mice." (PMID 29631601, 2018). "However; lithium's inhibition of GSK3B has also been postulated to have beneficial effects in Alzheimer's disease via reducing tau phosphorylation and neurofibrillary tangle formation as well as inhibiting autophagy via increasing mTOR signaling." (PMID 30425653, 2018). "Moreover, research has also demonstrated that inhibition of GSK-3β improves cognition during oxidative stress in a mouse model of Alzheimer’s disease." (PMID 26838164, 2016). "AZD1080, a novel GSK-3β inhibitor, has been reported to play a pivotal role in attenuating the downstream detrimental effects of signaling pathways activated by multiple stimuli relevant to Alzheimer's disease." (PMID 27050373, 2016). "Apart from tumors, GSK-3β has been implicated in the progression of multiple human conditions including Alzheimer`s disease, bipolar disorder and noninsulin-dependent diabetes mellitus." (PMID 27579985, 2016). "In an Alzheimer's disease research, it was revealed that estrogen receptor and GSK3B could change the tau protein phosphorylation, indicating sex involved in pathogenesis of this neurodegenerative disease." (PMID 24779391, 2014). "WWOX is involved in binding and regulating GSK-3β activity, and this limits Tau hyperphosphorylation, neurite outgrowth in neuronal differentiation, and formation of neurofibrillary tangles (NFTs) and senile plaques in Alzheimer's disease (AD)." (PMID 25537520, 2014). "GSK3β is involved in a wide range of physiological functions, and is presumed to act in the pathogenesis of neurological diseases, from bipolar disorder to Alzheimer’s disease (AD)." (PMID 23705847, 2013).
Alzheimer disease (continued). "Interestingly, both GSK-3β and TRPM2 channels have been implicated in a number of overlapping pathophysiological processes ranging from pancreatic insulin secretion to Alzheimer's disease." (PMID 22188973, 2011). "Interestingly, our findings showing increases in both p-GSK-3β and GSK-3β-Ser9 are similar to that seen reccently in Alzheimer's disease, where GSK3β was found to be phosphorylated to a similar extent at both the regulatory sites, Ser9 and Tyr216." (PMID 21445308, 2011). "Moreover, high levels of S100B cause GSK3β-dependent hyperphosphorylation of τ protein (a hallmark of Alzheimer disease) via RAGE-dependent activation of JNK and upregulation of Dickopff-1, a stimulator of GSK3β activity, in human neural stem cells." (PMID 20827421, 2010). "This accumulating evidence suggests that activation of GSK-3β may be involved in NFT formation and neuronal loss in neurodegenerative diseases, including Alzheimer's disease (AD)." (PMID 18958152, 2008). "In d-galactose/aluminum chloride (d-gal/AlCl3)-induced Alzheimer’s disease (AD)-like rat models, CA extracts significantly improved spatial memory performance and motor dysfunction by alleviating tau pathology and oxidative stress through the activation of the Akt/GSK3β pathway." (PMID 40932246, 2025). "Therefore, the inactivation of GSK3-β may be an important neuroprotective factor in Alzheimer’s disease, since activated GSK3 affects β-amyloid metabolism and tau protein phosphorylation." (PMID 39513900, 2024). "Alzheimer’s disease (AD) is a neurodegenerative disorder associated with the dysregulation of several key enzymes, including acetylcholinesterase (AChE), cyclooxygenase-2 (COX-2), glycogen synthase kinase 3β (GSK-3β), β-site amyloid precursor protein cleaving enzyme 1 (BACE-1), and caspase-3." (PMID 39598743, 2024). "In a murine model of Alzheimer disease (AD), a phosphorothionated antisense against glycogen synthase kinase (GSK)-3β, GAO, lead to an improvement of learning and memory abilities coupled with a reduction of protein oxidation and lipid peroxidation markers." (PMID 38044945, 2023). "Thus, targeting GSK-3β may inhibit Tau hyperphosphorylation and halt the progression of Alzheimer’s disease." (PMID 38139125, 2023). "Furthermore, due to the biological activity of GSK-3β, we speculate that 9-butyl-harmol also has the potential to serve as a candidate for diabetes mellitus and Alzheimer’s disease." (PMID 36877059, 2023). "The ability of GSK-3β to contribute to the phosphorylation of tau and Aβ production provides a link between the two pathologies and suggests a key role for GSK-3β in the pathogenesis of Alzheimer’s disease, where zinc ions may be involved through activating GSK-3β." (PMID 35740910, 2022). "Additionally, the main targets APP and GSK3β in the Alzheimer’s disease pathway were verified." (PMID 35462916, 2022). "Therefore, a hypothesis suggests that GSK3β deregulation in neurons may be a key point in developing Alzheimer’s disease." (PMID 36614030, 2022). "Interestingly, both miR-26a, as part of a signature group of miRNAs known to be deregulated in Alzheimer's disease, and GSK3β, which has shown increased activity leading to tau hyperphosphorylation in various Alzheimer's disease models, have been implicated in neurodegenerative processes." (PMID 31964775, 2020). "This implies a role for GSK3B in brain development as well as neurodegeneration, which may have important implications for the treatment of disorders such as Alzheimer’s disease, frontotemporal dementia, Parkinson’s disease and schizophrenia, that have been associated with GSK3B." (PMID 23951236, 2013). "Inducing GSK-3β Ser-9 phosphorylation through AMPK, a kinase, liberates NRF2 and improves cognitive impairment and pathological features in Alzheimer’s disease." (PMID 41277868, 2026). "The mRNA levels of GSK3β and APP were significantly increased in the Alzheimer’s disease rats group compared with normal rats." (PMID 39850118, 2025).
Alzheimer disease (continued). "In T1DM, some of the terms annotated were related to myelin dysregulation (ARHGEF6, CNP, NADK2, PSAP, SLC25A12) and other neurological disorders, such as Alzheimer’s disease (i.e., POA2, APOC1, APOC3, CNP, GSK3B, PON1, PSAP, SELENBP1) or movement disorders." (PMID 39901093, 2025). "A previous study reported that icariin (ICA) alleviated Alzheimer’s disease pathology by regulating the expression of MEG3 and MALAT1 lncRNAs and modulating the AKT/GSK3β signaling pathway." (PMID 40869265, 2025). "Alzheimer’s disease and nuclear-relevant phosphorylated forms of tau can be produced by incubation with tau’s kinases, including MAPK, cdk5, CAMKII, GSK-3β, and PKA75." (PMID 38429335, 2024). "In a mouse model of Alzheimer’s disease, Se supplementation promoted hippocampal neurogenesis through the PI3K/AKT/GSK-3β/Wnt signaling pathway." (PMID 38289713, 2024). "Mor prevents Alzheimer’s disease by reducing tau phosphorylation via PI3K/Akt, calpain/GSK-3β, and Src/PP2Ac pathways." (PMID 39301568, 2024). "Here, we combined structural elements found in inhibitors of three kinases—GSK-3β, IKK-β, and ROCK-1—to develop multifunctional ligands targeting processes involved in the progression of Alzheimer’s disease." (PMID 38893493, 2024). "Recently, harmine derivatives were identified as GSK-3β/DYRK1A dual inhibitors, thereby serving as potent candidates for Alzheimer’s disease." (PMID 36877059, 2023). "Two potential target genes, GSK3B and BACE1, have been deemed possible candidates as disease-modifying agents for Alzheimer’s disease due to their involvement in amyloid-beta and tau production, as well as their ability to enhance cognitive functions." (PMID 37444065, 2023). "It is thought that the relationship between GSK3β and COX-2 is a significant contributor to the pathogenesis of Alzheimer's disease (AD)." (PMID 37638222, 2023). "According to the Alzheimer’s disease pathway (hsa05010), we listed the main AO targets that regulate tau phosphorylation, such as MAPT, GSK3B, CDK5, CDK5R1, and CAPN1." (PMID 36533181, 2022). "By regulating GSK-3β and Tau protein, the PI3K/Akt signaling pathway affects a variety of CNS diseases, such as Alzheimer’s disease, Parkinson’s disease, and Huntington’s disease." (PMID 35592257, 2022). "Glycogen synthase kinase 3 beta (GSK-3β) is an evolutionarily conserved serine-threonine kinase dysregulated in numerous pathologies, such as Alzheimer’s disease and cancer." (PMID 35409221, 2022). "In a cell model of Alzheimer’s disease, the effects of ICT on decreasing the levels of GSK-3β and phosphorylated Tau have been found to be slightly better than that of ICA." (PMID 34829948, 2021). "In the pathway analysis of KANPHOS, a search for Alzheimer’s disease pathways reveals that CDK5 and GSK3β are important kinases involved in the pathogenesis of Alzheimer’s disease." (PMID 35011609, 2021). "In line with this evidence in an in vitro model of Alzheimer’s disease, CBD treatment suppressed the hyperphosphorylation of tau protein-mediated to β-catenin and GSK-3β, in Aβ-stimulated PC12 neuronal cells." (PMID 33171772, 2020). "Noticeably, GSK3B is involved in KEGG pathways, such as TCR- and BCR-signalling and Alzheimer’s disease pathways." (PMID 31666081, 2019). "Further study is required on the roles of GSK3α and GSK3β in neuronal physiology, especially in different forms of synaptic plasticity, as well as in GSK3-related diseases of the nervous system (e.g., Alzheimer’s disease, bipolar disorder)." (PMID 26207897, 2015). "Moreover, based on the PPI network, PTPN1 has direct interactions with GSK3B, PIK3R1, and CAPN1 in the Alzheimer’s disease pathway." (PMID 38612872, 2024). "When applied to the four NDs Alzheimer's disease (AD), Huntington's disease, and spinocerebellar ataxia types 1 and 3, we predicted multiple members of the insulin pathway, including PDK1, Akt1, InR, and sgg (GSK‐3β), as common modifiers." (PMID 37984409, 2023).
Alzheimer disease (continued). "Moreover, microRNA-128 suppressed tau phosphorylation and reduced amyloid beta aggregation via targeting GSK3β, APPBP2, and mTOR in Alzheimer’s disease." (PMID 37727513, 2023). "GSK3B inhibitors also have the most progress with preclinical and clinical trials, but many of these drugs are used to treat cancer rather than Alzheimer’s disease." (PMID 37444065, 2023). "In this work, protein-protein interaction analysis was conducted based upon the genes from a clinical database to identify the top protein targets with most data-indicated involvement in Alzheimer’s disease, which include ABCA1, CYP46A1, BACE1, TREM2, GSK3B, and SREBP2." (PMID 37444065, 2023). "According to the higher relevant Alzheimer disease pathway and genes from network pharmacology results, two targets including amyloid beta precursor protein (APP) and glycogen synthase stimulate 3β (GSK3β) were further validated based on western blot experiments." (PMID 35462916, 2022). "Two genes enriched in Alzheimer’s disease pathway, APP and GSK3β, were further validated." (PMID 35462916, 2022). "With respect to pathological conditions, knock-down of GSK3α, but not GSK3β, ameliorated amyloid plaque loads and memory deficits in an Alzheimer’s disease (AD) mouse model." (PMID 33572709, 2021). "The manuscript “GSK3ß impairs KIF1A transport in a cellular model of Alzheimer’s disease but does not regulate motor motility at S402 “ characterizes the contribution of GSK3β on axonal transport in AD model." (PMID 33067366, 2020). "Two phase II clinical trials with the GSK‐3β inhibitor, Tideglusib, showed no clinical benefits in Alzheimer's disease and progressive supranuclear palsy." (PMID 29997171, 2018). "Despite experimental evidence supporting the therapeutic effect of GSK3β inhibition, none of GSK3β inhibitors was approved for treatment of diseases such as diabetes mellitus, Alzheimer's disease, and cancer." (PMID 28423558, 2017). "In Alzheimer’s disease (AD), GSK3β produces pathological and abnormal phosphorylation of tau5–7, but it is not known how GSK3β becomes to phosphorylate tau abnormally in AD brains." (PMID 28819213, 2017). "Glycogen synthase kinase 3beta (GSK3β), a downstream molecule of Akt or PKA, is involved in many physiological and pathological processes, such as synaptic plasticity, tau pathology of Alzheimer's disease and ethanol-induced neuronal excitotoxicity." (PMID 27582689, 2016). "Intriguing, the pharmacological manipulation of Wnt pathway, using GSK3β inhibitors (lithium chloride, SB216763), is a promising therapeutic approach for several pathologies such as diabetes, stroke, mood disorders, inflammation, and Alzheimer’s disease." (PMID 26056602, 2015). "Heterocyclic thiadiazolidinones, TDZD-8 and TDZD-20, are two non-competitive inhibitors that were developed to inhibit GSK3β, and in clinical trials for treatment of Alzheimer's disease." (PMID 21829721, 2011). "Moreover, it is possible that, in Alzheimer's disease, aberrant HDAC6 levels are induced by increased activity of GSK3β." (PMID 20520769, 2010). "In particular, abnormal mitochondrial transport, which has been observed in such disorders as Alzheimer's disease and Parkinson's disease, could result from the misregulation of HDAC6 by GSK3β." (PMID 20520769, 2010). "All these data suggest the potential use of this site‐specific inhibitor of GSK‐3β as a helpful tool for the treatment of brain/mental/psychiatric diseases that depend on GSK‐3β activation, such as mood disorders, or even neurodegenerative diseases such as tauopathies and Alzheimer's disease." (PMID 41020548, 2026). "↓ of kinase expression (5 μM): GSK3β, CDK5, DYRK1A, CAMK2A, MAPK1, MAPK12, MAPK14.Modulation of the hGMSC transcriptome, ↓ expression of genes involved in Alzheimer's pathogenesis.↓ expression of GSK3b and p‐GSK303B2, which plays a key role in Alzheimer's disease." (PMID 39653426, 2025).
Alzheimer disease (continued). "Interestingly, the decrease in proteins like glycogen synthase kinase 3 beta (GSK3β) or CDK5, the most relevant kinases engaged in Alzheimer’s disease pathogenesis, reduces the phosphorylation of the microtubule-binding protein tau, likely contributing to cognitive function restoration." (PMID 39451238, 2024). "Additionally, GSK-3β has been reported to be a common link between T2DM and Alzheimer’s disease." (PMID 39458839, 2024). "In another model of Alzheimer’s disease by neuronal damage induced by the administration of β amyloid 25–35 in the hippocampus of rats, the Litchi chinensis seed extract was able to attenuate the lesion and improve the cognitive functions of rats through the AKT/GSK-3β pathway." (PMID 37299465, 2023). "Both the activation of glycogen synthase kinase‐3β (GSK‐3β) and the presence of ApoE ε4 genotype have been found to respectively correlate with cognitive decline in patients with type 2 diabetes mellitus (T2DM), who further show a high incidence of developing Alzheimer's disease." (PMID 37700547, 2023). "For example, GSK3B has been studied as a target for drug discovery in the treatment of nervous system disorders, and a brain penetrable and orally active GSK3 inhibitor has been reported as a clinical candidate for Alzheimer’s disease and progressed into Phase 1 clinical trials." (PMID 35096583, 2021). "Furthermore, the activity of GSK3α, but not GSK3β, is required for the production of amyloid-β in the brain of patients with Alzheimer's disease." (PMID 17683539, 2007). "GSK3B may play a role in neuroinflammation, neuronal apoptosis, and accumulation of phosphorylated tau in AD, while KCNIP3 may play a functional role in the neurobiology of Alzheimer's disease by being part of these gene interaction networks commonly associated with neurodegenerative processes." (PMID 40537925, 2025). "Moreover, it is not reported whether and how glycogen synthase kinase‐3β (GSK‐3β), a crucial kinase in insulin resistance and Alzheimer disease‐like pathologies, play a role in linking ApoE ε4 and cognitive impairment." (PMID 37700547, 2023). "Considering the multiple signaling GSK-3β involved and the wide distribution of GSK-3β, it is possible that this synaptic function of SHANK3B may also be important for the pathology of many other neuropsychiatric and neurodevelopmental disorders, such as Alzheimer’s disease and Schizophrenia." (PMID 31749684, 2019). "In Alzheimer ́s disease, active GSK-3ß leads to hyper-phosphorylation of Tau probably due to lack of Akt/PKB activity transducing an increase in GSK-3β activity." (PMID 27579985, 2016). "This study showed that the synthetic compound aloisine A (compound 50) is highly selective for GSK-3β (IC50 = 0.65 μM), but still GSK-3β was evaluated against cancers and neurodegenerative disorders such as Alzheimer’s disease but not for heart disease treatment." (PMID 29134113, 2017).